PPARA (peroxisome proliferator activated receptor alpha)
Diseases named in the same sentence as PPARA in open-access papers (continued):
Sharing a sentence is not in itself a finding about the gene and the disease.
COVID-19 (27 papers, 2020 to 2025). A disease caused by infection with severe acute respiratory syndrome coronavirus 2. "Following these studies, the recent emerging literature has also reported that activation of PPARα, PPARβ/δ, and PPARγ is inversely related to pulmonary fibrosis caused by chronic inflammation in COVID-19 patients." (PMID 36875108, 2023). "As a result, the decrease in PPARα due to COVID-19 can potentially be the main factor in the cause of pulmonary inflammation and be involved in the pathogenesis of acute lung injury." (PMID 34057580, 2021). "We identified PTEN, mTOR, and PPARA as possible core target genes for metformin in the treatment of COVID-19/LUAD by screening genes based on their expression levels." (PMID 38811809, 2024). "Intriguingly, zinc supplementation has also been reported to have potential health benefits for managing inflammation in COVID-19 by suppressing the expression of many cytokines and adhesion molecules through increasing the expression of PPARα." (PMID 36875108, 2023). "The PPARα agonist fenofibrate is a potential adjunctive coronavirus disease (COVID-19) therapy; the material exhibits anti-inflammatory and anti-thrombotic activities." (PMID 36831317, 2023). "It inhibits the phospholipid in infected cells as it possesses peroxisome proliferator-activated receptor alpha (PPARα) agonist activity, thus affecting the pathways of lipid metabolism in the lung cells of COVID-19 patients." (PMID 35877432, 2022). "Clinical trials using fenofibrate, a PPARα agonist, are in course in the United States as a metabolic intervention in COVID-19,1 which evidence the importance of lipid metabolism dysfunction in COVID-19 pathogenesis and progression." (PMID 33716771, 2021). "Furthermore, Cytoscape software was used to visualize the degree of each gene in the PPI network, and PTEN, mTOR, and PPARA were identified as core targets for metformin treatment against COVID-19/LUAD due to their high degree within the network." (PMID 38811809, 2024). "Moreover, several recent studies also reported that the reduction in PPARγ and PPARα is directly related to acute pulmonary inflammation in COVID-19 and the shift of the disease from mild to severe and, finally, death." (PMID 36875108, 2023). "A link has been suggested between severe acute respiratory syndrome coronavirus 2 (SARS-CoV-2) virus infection and PPARα activity in the context of lipid uptake, lipotoxicity, and vascular inflammation." (PMID 36831317, 2023). "Interestingly, a recent study proposes PPARα and PPARγ agonists as adjuvants for COVID-19 vaccine, thanks to their ability to enhance both B and T memory cells through different mechanisms." (PMID 35053112, 2022). "SARS-CoV-2 changes lipid profile in the lung epithelial cells by interfering in PPARα and PPARγ expression or activity, culminating in lipotoxicity, which became these molecules an attractive potential therapeutic target in COVID-19 patients." (PMID 33716771, 2021). "The results indicated that both PPARγ and PPARα are downregulated, while SOX17 and RUNX1 gets upregulated in COVID-19 patients." (PMID 34407143, 2021). "In contrast to other viral diseases such as COVID-19, it has been suggested that OEA, which is also upregulated only in TBE patients, is responsible for the downregulation of NFκB-related gene expression and also modulates the effects partially mediated by PPARα." (PMID 38438941, 2024). "The PPARα agonist palmitoylethanolamide (PEA) has well-known anti-inflammatory effects, and a very recent study identified the putative mechanisms by which this compound could represent a promising adjuvant in the current COVID-19 therapeutic protocols." (PMID 35053112, 2022). "As a peroxisome proliferator-activated receptor alpha (PPARα) agonist, fenofibrate prevents phospholipid accumulation within SARS-CoV-2 infected cells, blocking viral replication as well as pathogenesis by affecting the pathways of lipid metabolism in lung cells of COVID-19 patients." (PMID 34582497, 2021).
lung fibrosis (27 papers, 2005 to 2025). "A recent study demonstrated that reduced PPARα in AECIIs is associated with senescence and promotes lung fibrosis." (PMID 38658970, 2024). "Namely, similar to pulmonary fibrosis, the expression of PPARA and IGFBP2 significantly decreased, and that of the senescence marker p21 (CDKN1A) increased in the A549 cells exposed to DEP." (PMID 39103936, 2024). "One study concluded that the peroxisome proliferator-activated receptor alpha (PPARα) agonist pemafibrate attenuates pulmonary fibrosis by inhibiting myofibroblast differentiation and ECM accumulation." (PMID 36767821, 2023). "Fenofibrate (FF), a peroxisome proliferator‐activated receptor‐alpha (PPAR‐α) agonist and a lipid‐lowering agent, can decrease experimental pulmonary fibrosis." (PMID 34228906, 2021). "In the mouse model of lung fibrosis induced by bleomycin, a PPARα agonist significantly inhibited the fibrotic response, while PPARα knockout mice developed more serious fibrosis." (PMID 17710235, 2007). "In conclusion, these data suggested that HMGCS2 facilitated lipid metabolism of AECIIs through interacting with PPARα, which promoted the expression of CPT1A and CPT2 in mice lung fibrosis models." (PMID 38658970, 2024). "In conclusion, these data suggested that HMGCS2 facilitated lipid metabolic of AECIIs through interacting with PPARα to promote the expression of CPT1A and CPT2 in mice lung fibrosis models." (PMID 38658970, 2024). "Moreover, activation of peroxisome proliferator-activated receptor α (PPARα) participating in the processes of both physiological and toxicological response to various endogenous or exogenous substances may also protect against lung fibrosis." (PMID 27827897, 2016). "Our study adds to these previous findings by showing that PPARα agonists may also be effective in blocking recruitment of monocytes, which play a pivotal role in the pathophysiology of COPD, as well as of pulmonary fibrosis." (PMID 16091136, 2005). "Therefore, we assumed that HMGCS2 might act as a transcriptional coactivator of PPARα in regulating the expression of PPARα target genes such as CPT1A and CPT2 in lung fibrosis." (PMID 38658970, 2024).
diabetic retinopathy (26 papers, 2012 to 2025). "Peroxisome proliferator-activated receptor alpha (PPARα) is associated with diabetic retinopathy (DR), and the underlying mechanism is still unclear." (PMID 34362460, 2021). "Of the three sub-types, PPARα is most implicated in the underlying mechanisms of diabetic retinopathy." (PMID 32326149, 2020). "PPARα is another key regulator gene expression controlling cellular metabolism implicated in the development of diabetic retinopathy." (PMID 24736612, 2014). "Activation and modulation of PPARα as a means for diabetic retinopathy treatment has been widely investigated in recent years and demonstrated promising effects in clinical trials." (PMID 39941353, 2025). "Fenofibrate, a PPARα agonist commonly used to lower triglyceride, was shown to slow the progression of diabetic retinopathy in the Fenofibrate Intervention and Event Lowering in Diabetes (FIELD) study." (PMID 41438090, 2025). "More recently, PPARα agonist fenofibrate has been reported to have a robust therapeutic effect on diabetic retinopathy in type 2 diabetic patients." (PMID 36943878, 2023). "Two independent, prospective clinical studies reported robust therapeutic effects of PPARα agonist fenofibrate on diabetic retinopathy in type 2 diabetic patients." (PMID 36943878, 2023). "In summary, PPARα activation by FA alleviated IR-induced damage to the structure and function of RGCs, actions that are consistent with its protective effects in diabetic retinopathy or oxygen-induced proliferative retinopathy." (PMID 35004756, 2021). "Two large clinical studies showed that fenofibrate, a commonly used peroxisome proliferator-activated receptor α (PPARα) agonist, has protective effects against diabetic retinopathy." (PMID 32616724, 2020). "A fibric acid derivative, Fenofibrate, is a peroxisome proliferator activated-receptor alpha (PPARα) agonist recently approved for the management of diabetic retinopathy (DR)." (PMID 28058263, 2016). "In recent years, several experimental and clinical studies have shown the beneficial effects of peroxisome proliferator-activator receptors (PPARs) agonists (in particular PPARα) in diabetic retinopathy." (PMID 23431285, 2013). "Ever since 1969 there has been clinical evidence of a beneficial effect of PPARα activation on diabetic retinopathy." (PMID 23431285, 2013). "Both PPARα and PPARγ have been proposed as candidates for treating diabetic retinopathy." (PMID 41438090, 2025). "This is consistent with our previous reports and other studies that PPARα agonists (pemafibrate or fenofibrate) increase serum levels of FGF21 as well as boost liver function to exert therapeutic effects in ischemic retinopathies such as diabetic retinopathy or ocular ischemic syndrome." (PMID 34502311, 2021). "Of therapeutic relevance, fenofibrate, a potent PPARα agonist originally considered to have roles in lipid regulation, anti-inflammation, and anti-apoptosis, has shown promise in clinical trials as a possible oral treatment option for diabetic retinopathy by preventing microvascular complications." (PMID 32326149, 2020). "A previous study demonstrated that PPARα, but not PPARβ or PPARγ, is down‐regulated in diabetic retinopathy." (PMID 37731202, 2023). "Among PPARα-bound genes, EIF1 is one of the overlapped genes with pemafibrate-induced genes; pemafibrate-treated HUVECs showed a reduced inflammatory reaction and protective effects against diabetic retinopathy." (PMID 35308095, 2022).
gastric cancer (26 papers, 2015 to 2025). A primary or metastatic malignant neoplasm involving the stomach. "Together, these results demonstrate that antagonizing miR-BART20-3p upregulates PPARα and concomitantly downregulates IL-6, reinforcing the functional miR-BART20-3p–PPARα–IL-6 axis in EBV-associated gastric cancer." (PMID 40732023, 2025). "Given PPARα’s established role in restraining pro-inflammatory cytokines such as IL-6, IL-1β, and TNF-α, and the importance of inflammation in gastric cancer progression, we next assessed whether loss of PPARα elevates inflammatory mediators in GC cells." (PMID 40732023, 2025). "In summary, our work uncovers a novel oncogenic axis in EBV-associated gastric cancer, whereby EBV-encoded miR-BART20-3p directly targets PPARα to unleash IL-6–driven inflammatory signaling, thereby promoting tumor cell proliferation and migration." (PMID 40732023, 2025). "Together, these data indicate that EBV infection upregulates miR-BART20-3p and concomitantly suppresses PPARα expression in gastric cancer, supporting a functional miR-BART20-3p–PPARα axis in EBVaGC progression." (PMID 40732023, 2025). "We then validated that miR-BART20-3p binds the PPARα 3′-UTR to suppress its expression and demonstrated that miR-BART20-3p promotes proliferation, migration, and IL-6 upregulation via PPARα inhibition in gastric cancer cells." (PMID 40732023, 2025). "To extend these findings to human tumors, we measured miR-BART20-3p and PPARα in EBV–negative (EBVnGC) and EBV-positive (EBVaGC) gastric cancer tissues." (PMID 40732023, 2025). "SDPR regulates the ERK/PPARα signalling axis by interacting with the ERK protein and regulates CPT1A at the transcriptional level, which is involved in FAO in gastric cancer." (PMID 37416765, 2023). "miR-21 and VEGF expression was upregulated in gastric cancer in vivo and in vitro, while PPARα was downregulated; expression of VEGF and PPARα was correlated with miR-21 levels." (PMID 34926688, 2021). "In this study, the potential target of HL-RG in the treatment of gastric cancer was studied Through PPI network analysis and molecular pairing, TGFB1, CCND1, MMP9, ERBB2, CAT, and PPARα may be the core targets of HL-RG in the treatment of RCC." (PMID 41305721, 2025).
coronary heart disease (24 papers, 2008 to 2026). "PPARα gene variants appear to be associated with higher plasma lipid levels and increased risk of coronary artery disease." (PMID 33728018, 2021). "A significant association was observed between coronary artery disease and PPARα genotypes." (PMID 22347658, 2011). "Clinical experiments have found significantly reduced levels of plasma interleukin-6 (IL-6), interferon-α (IFN-α), and C-reactive protein (CRP) after taking the PPARα agonist (fibrate) in patients with coronary heart disease confirmed by angiography." (PMID 33728018, 2021). "In ischemic heart disease, the expression and/or DNA binding activity of the PPARα-RXR complex is markedly diminished by hypoxia, which results in decreased expression of genes encoding enzymes involved in mitochondrial FAO and oxidative phosphorylation pathways." (PMID 27955667, 2016). "Therefore, we aimed to observe the effects of combined PPARα/γ agonists on T2DM patients with coronary artery disease (CAD)." (PMID 23408783, 2013). "However, in contrast to patients with idiopathic dilated cardiomyopathy (DCM) and ischemic heart disease (IHD), patients with mitochondrial cardiomyopathy (MIC) have increased expression of genes involved in fatty acid metabolism, including Ucp2, Cpt1, Pparα and Pgc1-α." (PMID 24945157, 2014).
endothelial dysfunction (24 papers, 2010 to 2026). In vascular diseases, endothelial dysfunction is a systemic pathological state of the endothelium (the inner lining of blood vessels) and can be broadly defined as an imbalance between vasodilating and vasoconstricting substances produced by (or acting on) the endothelium. "PPARα activation by its agonist fenofibrate has recently been shown to attenuate several mediators of vascular damage including inflammation, endothelial dysfunction, and angiogenesis during DR and AMD27,28,60–66." (PMID 33145027, 2020). "PPARα's beneficial effects are multifaceted, and PPARα downregulation has been found to play important roles in vasoregression, endothelial dysfunction, vascular hyperpermeability, and pathological angiogenesis." (PMID 25705219, 2015). "PPARα's abilities to decrease oxidative stress, inflammation, and endothelial dysfunction resulting from a variety of pathophysiological events undoubtedly play significant roles in its therapeutic effects." (PMID 25705219, 2015). "PPARα has protective effects in endothelial dysfunction, hypertension, vasoregression, pathological neovascularization, and vascular hyperpermeability." (PMID 25705219, 2015). "Through this pathway, PPARα attenuates vascular damage in various ways, including reducing lipotoxicity, inflammation, the generation of reactive oxygen species, endothelial dysfunction, and angiogenesis in DPN." (PMID 24392081, 2014). "Activation of PPARα attenuates or inhibits several vascular damage mediators, including lipotoxicity, inflammation, reactive oxygen species generation, endothelial dysfunction, and thrombosis." (PMID 24392081, 2014). "We and others have also demonstrated that PPARα has beneficial effects in the diabetic microvasculature, and these effects may be due in part to decreased endothelial dysfunction in diabetic conditions." (PMID 25705219, 2015). "Thus, the increase in contraction indicated that there was endothelial dysfunction in Pparα−/− mice." (PMID 26649033, 2015). "It is therefore likely that PPARα restoration of endothelial dysfunction may be responsible in part for its neuroprotective effects in these diseases." (PMID 25705219, 2015). "The endothelial dysfunction that we observed in Pparα−/− mice could also be due, in part, to the decrease in eNOS expression." (PMID 26649033, 2015). "Increased apoptotic cell death and endothelial dysfunction via inactivation of the PPARα-AMPK-PGC-1α pathway and their downstream PI3K-Akt-eNOS-NO pathway were noted in db/db mice, human umbilical vein endothelial cells (HUVECs) and human Schwann cells (HSCs) in high-glucose media." (PMID 24392081, 2014). "A substantial body of in vivo evidence demonstrates that activation of all three PPAR subtypes—via agonists like fenofibrate (PPARα), rosiglitazone (PPARγ), and GW501516 (PPARβ/δ) —confers potent protection against endothelial dysfunction and robustly promotes reparative angiogenesis." (PMID 41216186, 2025). "Moreover, SIRT1 prevents endothelial dysfunction via deacetylation of PGC-1α and PPARα, which reduces NADPH oxidase activity and improves NO activation." (PMID 38095615, 2023). "PPARα and PPARγ mRNA are greater in young and adult SHR mesenteric arteries compared to WKY (but not in other tissues), and thizaolidinedione PPARγ agonists attenuated remodeling and endothelial dysfunction in mesenteric resistance arteries in response to angiotensin II or endothelin-1." (PMID 28264510, 2017).
Glucose intolerance (24 papers, 2010 to 2025). Glucose intolerance (GI) can be defined as dysglycemia that comprises both prediabetes and diabetes. "Because pemafibrate is reported to improve glucose intolerance in mice treated with a high fat diet and a novel selective PPARα modulator, it may affect KATP channels or insulin secretion." (PMID 37697384, 2023). "AdipoRon showed very similar effects to adiponectin in muscle and liver, such as an activation of AMK and PPARα pathways, and ameliorated IR and glucose intolerance in mice fed a high-fat diet, which was completely obliterated in adipoR1 and AdipoR2 double-knockout mice." (PMID 24864249, 2014). "As such, combined PPARα and GRα agonist treatment might hold a promise of therapeutic benefit when able to cooperatively enhance anti-inflammatory effects, while circumventing (at least) the side effect of GC-induced glucose intolerance." (PMID 31447832, 2019).
dyslipidaemia (23 papers, 2007 to 2025). "Presence of C allele showed a positive association with CAD (OR = 2.9; 95% CI [1.65–4.145]; P = .009) and also with dyslipidaemia (OR = 2.95, 95% CI (1.5–4.39); P < .05).Impaired lipid metabolism in carriers of the PPARα Intron 7C allele is possibly responsible for the predilection to CAD." (PMID 22347658, 2011). "Furthermore, statin-mediated expression of Pparα may underlie the molecular mechanism by which fibrates, a group of strong PPARα agonists used to treat dyslipidaemia, amplify the risk of severe muscle damage on statins." (PMID 28793934, 2017). "Fenofibrate is an established drug for dyslipidaemia known to act on PPARα pathways; however, it is unclear if PPARα is similarly involved in its anti-tumour activity." (PMID 38474047, 2024). "Fenofibrate, a peroxisome proliferator-activated receptor alpha (PPARα) agonist, is frequently used with statins to treat patients with dyslipidaemia and cardiovascular risk." (PMID 30279504, 2018). "Taken together, in vitro evidence for pemafibrate showed enhanced potency and selectivity for PPARα, suggesting added potential for management of dyslipidaemia." (PMID 28978316, 2017). "From the clinical perspective, the development of a novel SPPARMα with increased selectivity, high potency, as well as an improved safety profile compared with current PPARα agonists offers advantages in patients with atherogenic dyslipidaemia." (PMID 28978316, 2017). "PPARα is the molecular target of the fibrate class of lipid-lowering drugs, which have been widely used for decades in the treatment of dyslipidaemia." (PMID 17327920, 2007). "Selective PPARα modulators–SPPARMα agents—could well provide one approach to resolving this challenge, and offer a more accessible therapeutic approach to managing this dyslipidaemia." (PMID 28978316, 2017). "The available data show the benefits of applying the SPPARM concept to PPARα, showing effective lowering of TGs, as well as other atherogenic measures, notably VLDL- and remnant cholesterol, in statin-treated patients with atherogenic dyslipidaemia." (PMID 28978316, 2017).